CTPS1 (CTP synthase 1)
Description:
CTP synthase involved in the de novo synthesis of CTP, a precursor of DNA, RNA and phospholipids. Catalyzes the ATP-dependent amination of UTP to CTP with either L-glutamine or ammonia as a source of nitrogen. CTPS1 CTP synthase activity plays a crucial role in the proliferation of activated lymphocytes and immunity; additional CTP being required to meet increased demand for DNA, RNA and lipid membrane biosynthesis in proliferating lymphocytes. In addition to CTP synthase activity, also acts as a protein deamidase that catalyzes the side chain deamidation of specific asparagine residues of proteins to aspartate. Acts as a negative regulator of innate immunity by mediating deamidation of 'Asn-85' of IRF3, preventing IRF3 from binding DNA (By similarity). Facilitates chromatin relaxation in response to DNA damage by mediating deamidation of 'Asn-76' and 'Asn-77' of histone H1, thereby promoting subsequent acetylation of histone H1 at 'Lys-75' (H1K75ac), increasing chromatin accessibility to facilitate the recruitment of DNA repair proteins.
Synonyms: CTPS; GATD5A; GATD5; IMD24
Tractability: Small molecule: a structure with a bound ligand is known; a high-quality ligand is known. PROTAC: ubiquitination databases record sites on it; its protein half-life has been measured; a small molecule that binds it is known.
Target class: Enzyme; Ligase
Gene: Protein-coding gene on chromosome 1 (40,979,300 to 41,012,565, forward strand). Ensembl gene ENSG00000171793.
Subcellular location: Cytoplasm, cytosol; Nucleus; Chromosome
Subcellular location (Human Protein Atlas): Cytosol; Actin filaments
Pathways (Reactome):
Metabolism: Interconversion of nucleotide di- and triphosphates
Gene Ontology:
Molecular function: CTP synthase activity; histone H1N76/N77 asparagine deamidase activity; identical protein binding; protein asparagine deamidase activity; protein binding
Biological process: B cell proliferation; CTP biosynthetic process; DNA repair-dependent chromatin remodeling; negative regulation of chromosome condensation; T cell proliferation; negative regulation of type I interferon production; nucleobase-containing compound metabolic process; pyrimidine nucleobase biosynthetic process; response to xenobiotic stimulus; 'de novo' CTP biosynthetic process; organophosphate biosynthetic process; pyrimidine nucleotide biosynthetic process
Cellular component: chromatin; chromosome; cytoophidium; cytoplasm; membrane; nucleus; cytosol
Genetic constraint (gnomAD): Loss-of-function variants: 19 observed, 65.95 expected, observed/expected ratio (o/e) 0.29, 90% interval 0.2 to 0.42. The upper end of that interval is the gene's LOEUF score, 0.42, which puts it in group 1 of 6, group 1 being the genes least tolerant of losing a copy. Missense variants: 377 observed, 647.75 expected, observed/expected ratio (o/e) 0.58, 90% interval 0.53 to 0.63. Synonymous variants: 223 observed, 223.35 expected, observed/expected ratio (o/e) 1, 90% interval 0.89 to 1.12.
Gene-disease validity (ClinGen):
ClinGen rates the evidence that CTPS1 causes each of these diseases.
severe combined immunodeficiency due to CTPS1 deficiency (autosomal recessive): Definitive.
Homologues: Orthologues: macaque CTPS1 (99% identical), dog CTPS1 (98% identical), pig CTPS1 (98% identical), chimpanzee CTPS1 (98% identical), mouse Ctps1 (98% identical), rat Ctps1 (97% identical), guinea pig CTPS1 (95% identical), rabbit CTPS1 (90% identical), tropical clawed frog ctps1 (89% identical), zebrafish ctps1a (87% identical), zebrafish ctps1b (86% identical), Drosophila melanogaster Ctps (66% identical), and 1 more. Paralogues in human: CTPS2 (74% identical).
Diseases named in the same sentence as CTPS1 in open-access papers:
CTPS1 is named in the same sentence as 39 diseases in open-access papers, as found by Europe PMC text mining. Sharing a sentence is not in itself a finding about the gene and the disease. The quoted sentences say what the papers report.
Immunodeficiency (9 papers, 2015 to 2025). Failure of the immune system to protect the body adequately from infection, due to the absence or insufficiency of some component process or substance. "The first evidence of the importance of CTPS1 in vivo was given by the identification of a hypomorphic mutation in CTPS1 within a cohort of patients with severe immunodeficiency." (PMID 40957650, 2025). "Partial CTPS1 deficiency in humans has previously been shown to lead to immunodeficiency, with impaired expansion of T and B cells." (PMID 38438357, 2024). "Other immunodeficiencies with specific susceptibility to EBV—such as CTPS1 deficiency—are characterized by altered nucleic acid metabolism leading to rapid T-cell exhaustion upon massive proliferation induced by EBV infection." (PMID 34183044, 2021). "CTPS1 plays a predominant role in selected immune cell populations – e.g. CTPS1-deficient patients present with a life-threatening immunodeficiency – making CTPS1 an interesting target for the development of highly selective immunomodulatory drugs." (PMID 33968048, 2021). "Loss function of mutation in CTPS1 results in a novel and life-threatening immunodeficiency in human, revealing the central role of CTP in lymphocyte proliferation." (PMID 27825122, 2016). "However, to date CTPS1-deficiency is the only genetic defect impairing the pyrimidine pathway with a clinical phenotype restricted to immunodeficiency likely explained by the hypomorphic nature of the CTPS1 mutation." (PMID 38438357, 2024). "Notably, inactivating CTPS1 mutations in human patients cause immunodeficiency, suggesting that rapid proliferation in this cell compartment is the physiological context of CTP depletion that requires adjustment of CTP synthase levels." (PMID 35239666, 2022). "In humans, CTPS1 deficiency causes combined immunodeficiency and has no developmental effect." (PMID 38438357, 2024).
breast carcinoma (5 papers, 2013 to 2024). "The results indicated that CTPS1 was highly expressed in TNBC tumor tissues than other breast cancer subtypes or normal breast tissues in all three GEO datasets (all p < 0.001)." (PMID 34991621, 2022). "To investigate the function role of CTPS1 in TNBC cells, we firstly measured CTPS1 levels in several breast cancer cell lines." (PMID 34991621, 2022). "Furthermore, the enhanced expression levels of YBX1 and its correlated gene CTPS1 were able to predict poor outcomes of breast cancer." (PMID 30647855, 2018). "YBX1 and CTPS1 as well as ESR1 and CTPS1 were found to be independently associated with the prognosis, supporting the idea that PRIN2 and PRIN5 play important roles in the prognosis of breast cancer patients." (PMID 30647855, 2018). "For TCGA database, the expression of CTPS1 was also significantly elevated in TNBC tumor tissues compared to LuminalA, LuminalB breast cancer subtype and normal breast tissues (p < 0.001)." (PMID 34991621, 2022). "With the exception of UQCRH and LRP8, the expression levels of genes positively correlated with YBX1, such as CTPS1, FMNL2, CDC20, B3GNT5, MTHFD1L, and CDCA8, were significantly and positively correlated with the expression level of YBX1 in 13 breast cancer cell lines." (PMID 30647855, 2018).
triple-negative breast carcinoma (4 papers, 2022 to 2025). An invasive breast carcinoma which is negative for expression of estrogen receptor (ER), progesterone receptor (PR), and human epidermal growth factor receptor 2 (HER2). "Moreover, lower expression of CTPS1 was associated with a better prognosis of patients with triple-negative breast cancer." (PMID 34991621, 2022). "Collectively, these results demonstrate that elevated CTPS1 expression is a risk factor for triple-negative breast cancer patients and could be considered as a potential prognostic biomarker." (PMID 34991621, 2022). "Taken together, YBX1 could directly activate CTPS1 transcription by binding to its promoter region in triple-negative breast cancer." (PMID 34991621, 2022). "YBX1/CTPS1 is an important axis in the progression of triple-negative breast cancer." (PMID 34991621, 2022). "CTPS1 might be a promising prognosis biomarker and potential therapeutic target for patients with triple-negative breast cancer." (PMID 34991621, 2022). "For instance, in triple-negative breast cancer cells, YBX1 has been shown to directly activate the transcription of CTPS1 by binding to its promoter region." (PMID 40819060, 2025). "To further elucidate the functional role of CTPS1 in triple-negative breast cancer, we also conducted GSEA and WGCNA analysis with TNBC samples from GEO and TCGA databases to screen the gene and pathway sets related with CTPS1 expression." (PMID 34991621, 2022). "Our findings provide novel insight of CTPS1 in the progression of TNBC and suggest a new theoretical basis for the prevention and treatment of patients with triple-negative breast cancer." (PMID 34991621, 2022). "More specifically, proteomics analysis of triple-negative breast cancer (TNBC) patient samples revealed an increased expression of CTPS1 compared to para-tumor tissue, which is accompanied by a decrease in disease-free and overall survival of TNBC patients with high levels of CTPS1." (PMID 35203388, 2022).
B-cell lymphomas (3 papers, 2021 to 2023). "In contrast, B-cell lymphomas expressed more substantial levels of CTPS2, and a recent study suggested that the inactivation of both CTPS1 and CTPS2 is required to fully block Epstein Barr virus–driven B-cell proliferation." (PMID 37348953, 2023). "Another defect in CTP synthase 1 (CTPS1) also leads to fatal viral (EBV) infections which results in LP and non-Hodgkin B cell lymphoma." (PMID 35603189, 2022).
lymphoma (3 papers, 2021 to 2023). A malignant (clonal) proliferation of B- lymphocytes or T- lymphocytes which involves the lymph nodes, bone marrow and/or extranodal sites. "The high prevalence of B-cell driven EBV-associated diseases in people with CTPS1 deficiency raises the question of how EBV-driven lymphomas arise at high frequency, despite pronounced defects in lymphocyte metabolism." (PMID 34281398, 2021). "Because high levels of CTPS activity have been reported in cancer cells, in particular in lymphomas, inhibition of CTPS1 represents a potent therapeutic approach to block cancer progression." (PMID 37348953, 2023). "While our quantitative proteomic analyses identified that CTPS1 is approximately four times more abundant than CTPS2 in primary human B cells undergoing EBV-mediated growth transformation, EBV-infected lymphomas may compensate for CTPS1 deficiency by increasing CTPS2 levels and/or activity in vivo." (PMID 34281398, 2021). "Hypomorphic mutations of the de novo pyrimidine synthesis pathway enzyme cytidine 5′ triphosphate synthase 1 (CTPS1) suppress cell-mediated immunity, resulting in fulminant EBV infection and EBV+ central nervous system (CNS) lymphomas." (PMID 34281398, 2021).
pancreatic cancer (3 papers, 2020 to 2024). "HIF-1α target genes, TKT and CTPS1, regulating pyrimidine synthesis are associated with primary and metastatic pancreatic cancer tissues." (PMID 32707920, 2020). "TKT and CTPS1 co-localized with CAIX in PDAC tissue samples and in orthotopic pancreatic tumors." (PMID 32707920, 2020).
CNS lymphoma (2 papers, 2018 to 2021). "EBV+ CNS lymphomas are often observed in patients with CTPS1 deficiency, which are estimated to have 10 to 20% residual CTPS1 activity." (PMID 34281398, 2021). "While CRISPR CTPS1 knockout caused DNA damage and proliferation defects in lymphoblastoid cell lines (LCLs), which express the EBV latency III program observed in CNS lymphomas, double CTPS1/2 knockout caused stronger phenotypes." (PMID 34281398, 2021). "That CTPS1/2-deficient LCL growth could be restored by cytidine supplementation highlights the potentially important role of the CTP salvage pathway in B cells with the viral latency III program observed in CNS lymphoma." (PMID 34281398, 2021). "Interestingly, since oral intake may alter CNS pyrimidine levels, dietary cytidine and uridine restriction could potentially have antineoplastic effects in CTPS1-deficient patients with CNS lymphoma." (PMID 34281398, 2021). "Most CTPS1-deficient patients experienced EBV disease, including severe infectious mononucleosis, chronic EBV viremia, and EBV-associated primary CNS lymphomas." (PMID 34281398, 2021). "Two patients with CTP synthase 1 (CTPS1) deficiency have been treated with third party EBV-specific T cells for EBV-LPD and primary CNS lymphoma, and both had CRs after T cell therapy." (PMID 29616044, 2018). "Given our findings that CTPS2 supports proliferation of EBV-transformed CTPS1-deficient B cells, we speculate that CTPS2 plays important roles in the CNS lymphomas observed clinically." (PMID 34281398, 2021).
lymphoproliferative disorders (2 papers, 2018 to 2021). "Patients suffering from these genetic diseases exhibit a specific susceptibility to EBV‐driven lymphoproliferative disorders, which is very often the most severe phenotype associated with these conditions, even though some patients can develop other infections particularly in CTPS1 deficiency." (PMID 29282224, 2018). "Cytidine rescued CTPS1/2 deficiency phenotypes in EBV-transformed LCLs and Burkitt B cells, highlighting CTPS1/2 as a potential therapeutic target for EBV-driven lymphoproliferative disorders." (PMID 34281398, 2021).
viral infection (2 papers, 2024 to 2025). "One possible limitation of the use of CTPS1 inhibitors is to impair the immune response to viral infections including EBV reactivation (as it is observed in CTPS1-deficient patients)." (PMID 38438357, 2024). "Notably, SARS-CoV-2 infection did not increase CTPS1 protein levels, suggesting CTPS1 activation during viral infection." (PMID 40298378, 2025).
anaemia (1 paper, 2024). "Importantly, the study of these different mouse models also informs on possible adverse effects of treatments with CTPS1 inhibitors that might include anaemia, intestine injury, and lymphopenia." (PMID 38438357, 2024).
atherosclerosis (1 paper, 2024). A disease characterized by the build-up of fatty material and calcium deposition in the arterial wall resulting in partial or complete occlusion of the arterial lumen. "GART, TYMS, PPAT, and CTPS1 had the strongest association with inflammation, followed by atherosclerosis and cerebral infarction." (PMID 38995420, 2024).
Autoimmunity (1 paper, 2024). The occurrence of an immune reaction against the organism's own cells or tissues. "In this study, the authors examine the physiological consequences of CTP synthase (Ctps) 1 and 2 deletion in vivo and demonstrate that Ctps1 protects mice from fatal autoimmunity." (PMID 38438357, 2024). "We next tested whether deletion of Ctps1 could dampen pathological T-cell responses involved in autoimmunity and in inflammatory diseases." (PMID 38438357, 2024).
autoimmunity diseases (1 paper, 2024). "From these studies we concluded that CTPS1 could represent an attractive therapeutic target to selectively inhibit unwanted T/B cell proliferation involved in conditions such as autoimmunity diseases, T cell lymphoma/leukaemia or graft versus host disease (GvHD)." (PMID 38438357, 2024).
experimental autoimmune encephalomyelitis (1 paper, 2024). An autoimmune demyelinating disease of the central nervous system that is produced experimentally in animals by the injection of homogenized brain or spinal cord in Freund's adjuvant. "Deletion of Ctps1 in T cells or treatment with a CTPS1 inhibitor rescued Foxp3-deficient mice from fatal systemic autoimmunity and reduced the severity of experimental autoimmune encephalomyelitis." (PMID 38438357, 2024).
glioma (1 paper, 2024). A benign or malignant brain and spinal cord tumor that arises from glial cells (astrocytes, oligodendrocytes, ependymal cells). "Furthermore, we found that six downregulated genes, including pLCE1, PRPS2, FH, ASL, DTYMK, and CTPS1 were significantly increased in high-grade glioma tissues (p < 0.001)." (PMID 38438374, 2024).
infectious mononucleosis (1 paper, 2021). A condition characterized by an increase in mononuclear white blood cells and swollen lymph nodes, which is usually caused by infection with the Epstein-Barr virus. "However, with hypomorphic CTPS1 activity, patients often exhibit severe infectious mononucleosis, chronic active EBV and EBV+ CNS B-cell lymphomas." (PMID 34281398, 2021).
medulloblastoma (1 paper, 2025). A malignant, invasive embryonal neoplasm arising from the cerebellum. "Using both genetic and pharmacological means, they demonstrated that targeting CTPS1 is cytostatic in G3 medulloblastoma cells, reducing cellular proliferation but not driving apoptosis." (PMID 40471378, 2025). "CTPS1 is elevated in medulloblastoma tumor tissue compared to normal brain and correlates with MYC expression in tumors." (PMID 40471378, 2025).
ovarian carcinoma (1 paper, 2016). A malignant neoplasm originating from the surface ovarian epithelium. "We found that both of CTPS1 and CLIC1 are up regulated in ovarian cancer, while down regulated in CLIC1 KD cells." (PMID 27825122, 2016).